TNF (tumor necrosis factor)
Diseases named in the same sentence as TNF in open-access papers (continued):
Sharing a sentence is not in itself a finding about the gene and the disease.
acute kidney injury (continued). "BSHX alleviates glomerulosclerosis and tubulointerstitial injury and subsequently reverses renal failure in 5/6 nephrectomy rats, possibly via inhibition of the inflammatory responses mediated by TNF-α, NF-κB, TGF-β1, CTGF, PPARγ, and OPN." (PMID 24864155, 2014). "Savic and colleagues have done the study on protective effect of pentoxifylline therapy in patients with acute renal failure and concluded that pentoxifylline by inhibiting expression of protein related to tumor necrosis factor, can reduce cell death." (PMID 24734070, 2014). "Though in acute kidney injury the TNF-α gene, transforming growth factor β1 gene (TGF-β1), and interleukin 10 gene (IL-10) have more important effects on regulation of inflammatory response." (PMID 24282796, 2013). "An increased renal TNF-α level is correlated with indicators of renal failure in DM animals and patients." (PMID 23737649, 2013). "Also, in pathologic conditions like acute kidney injury, β2AR activation reduces inflammation by downregulating TNF-α and IL-6 via cAMP-PKA signaling." (PMID 40573268, 2025). "Additionally, a study performed using C3H/HeOuJ mice showed that lipopolysaccharides (LPS) stimulated the activation of TLR4, thereby triggering the release of tumor necrosis factor-α (TNF-α), which, consequently, induced renal failure." (PMID 38287815, 2024). "Regardless of the exact mechanism of the effect of nerolidol on TNF-α changes, the findings of this study are consistent with the findings reported in other models of acute kidney injury, such as lipopolysaccharide- and ischemia–reperfusion-induced acute kidney injury." (PMID 39457599, 2024). "Additionally, acute renal failure is accompanied by a significant increase in the levels of medium- and macromolecular substances such as hepatocyte growth factor, tumor necrosis factor, insulin-like growth factor and epithelial cell growth factor." (PMID 36694734, 2023). "Previous research showed that this metabolite ameliorated the inflammatory response by decreasing the expression of the cytokines TNF-α and IL-6 in a mouse model of sepsis-induced acute kidney injury (AKI), and this effect was dependent on silent information regulator sirtuin 1 (SIRT1) signaling." (PMID 38067518, 2023). "Moreover, the nephrotoxic responses to cisplatin were connected to TNF-alpha released by MCs during acute kidney injury induced by cisplatin." (PMID 36902051, 2023). "This renal failure was determined by higher levels of TNF-α, CRP, IL-6, and IL-10." (PMID 36851766, 2023). "Furthermore, it has been shown that TNF is required for acute renal failure, lung injury, and liver damage during LPS challenge." (PMID 36264059, 2022). "In addition, cytokines, such as TNF, IL-2, or IL-6, contribute to acute kidney injury and renal failure, as reported in critically ill COVID-19 patients." (PMID 36235704, 2022). "In addition, anti-TNF-α therapy was reported to improve cardiac fibrosis in rats with experimental diabetic cardiomyopathy and reduce renal fibrosis in rats with renal failure." (PMID 33460402, 2021). "In the kidney, TLR4-/- mice were shown to be resistant to endotoxin-induced acute renal failure, a phenomenon associated with a lack of a systemic TNF-α response." (PMID 30399158, 2018). "TNF-α has also been shown to be involved in renal disease, such as acute kidney injury." (PMID 29724888, 2018). "Acute inflammatory changes and TNF-α may also contribute to acute renal failure, and levosimendan has been previously shown to exert anti-inflammatory effects, the exact mechanisms of which are still not fully understood." (PMID 27684548, 2016). "The mRNA abundance of cytokines (IL-1α, IL-1β, IL-8, IL-10, TNF-α, TGF-β) and enzymes (5-LO, iNOS) was measured prospectively in blood leukocytes from 34 dogs with severe leptospirosis and acute kidney injury, including 22 dogs with leptospirosis-associated pulmonary hemorrhages." (PMID 26824356, 2016).
acute kidney injury (continued). "In conclusion, the current experimental study is the first to report on the additive beneficial effects of relatively small doses of fenofibrate and pioglitazone, against cisplatin-induced acute renal failure in rats and emphasizes the key role for TNF-α inhibition in this interaction." (PMID 26536032, 2015). "After acute kidney injury, renal dendritic cells produce the proinflammatory cytokines TNF, IL-6, C-C motif chemokine 2, and C-C motif chemokine 5, and depletion of dendritic cells before ischemia substantially reduces the levels of TNF produced by the kidney." (PMID 26089922, 2015). "TNF plays an important role in septic acute kidney failure development." (PMID 23476127, 2013). "All-in-all, our analysis does not point to the cytokines IL6, IFNγ and TNFα, that have classically been associated with low grade inflammation in cardiovascular disease and renal failure." (PMID 22957013, 2012). "Therefore, TNFα is a key mediator of LPS-induced acute renal failure, acting through its receptor, TNFR1." (PMID 22564340, 2012). "Extracellular HMGB1 drives cellular damage and inflammatory cascades in renal ischemic reperfusion injury (IRI) and plays a pivotal role in acute kidney injury (AKI) onset via Tumor Necrosis Factor (TNF)-α/HMGB1 inflammatory signalling." (PMID 39840112, 2024). "The resident MCs were suggested to contribute to the cisplatin-induced acute kidney injury (AKI) via TNF-alpha release." (PMID 36902051, 2023). "TNFα has been found to be a key cytokine in inducing apoptosis during progression of IRI in many contexts including acute kidney injury (AKI) models." (PMID 35874723, 2022). "Moreover, studies in vivo using a model of LOCBE-induced acute renal failure pointed out that kidneys of envenomed rats presented increased levels of superoxide, NO, MMPs and an excessive amount of proinflammatory cytokines such as TNF-α and IL-1β." (PMID 34209394, 2021). "Quercetin-3-O-glucoside can inhibit the expression of TNF-α, IL-1β and IL-6 and the activation of NF-κB, and simultaneously up-regulate the expression of Nrf-2 and HO-1, and inhibit the inflammation and oxidation to resist the induction of cisplatin of acute kidney injury in mice." (PMID 32748813, 2020). "Interestingly, in mice, the toxicity of TNF was shown to be aggravated by pan-caspase inhibition with carbobenzoxy-valyl-alanyl-aspartyl-[O-methyl]-fluoromethylketone (zVAD), resulting in hyperacute shock with increased mortality and renal failure." (PMID 32410851, 2020). "Likewise, in the acute phase of IRI, IRF4 acts as an endogenous regulator of myeloid cell activation, i.e., dendritic cells, suppresses TNF-α release from intrarenal myeloid cells, and thereby limits tubular cell necrosis, tissue inflammation, and acute renal failure 24 h and 5 days post-IRI." (PMID 31632388, 2019). "Moreover, it has been shown that the concentrations of PAF in plasma and urine are significantly increased in patients with acute renal failure during septic shock, accompanying with high levels of the pro-inflammatory cytokines including IL-1β, IL-6, IL-8, and TNF-α." (PMID 29950994, 2018). "In the present study, we investigated the association of 12 polymorphisms in six inflammatory-response genes (TNF, IL6, IL10, IL18, NFKB1 and NFKBIA) with risk of acute kidney injury (AKI) in children." (PMID 30429237, 2018). "Patients who developed renal failure had significantly elevated levels of IL-21 (p=0.006) and IL-23 (p=0.002), while those having liver involvement had significantly elevated levels of IL-21 (p=0.001), IL-23 (p=0.001), and TNF-α (p=0.008) compared to the healthy controls." (PMID 30123395, 2018). "Knowing that both circulating and tissue cytokines are important in triggering acute kidney injury induced by cisplatin, we analyzed serum levels and tissue expression of the main cytokines and observed lower serum levels of TNF-α and IL-1β in the CR group than in exercise group." (PMID 28303105, 2017).
acute kidney injury (continued). "Recently, we reported that transgenic (Tg) mice overexpressing HCaRG/COMMD5 in RPTs recovered rapidly from the inflammatory burst that increased TNF-α and IL-1β as well as infiltration of macrophages after acute kidney injury (AKI)." (PMID 24515317, 2014). "In addition, the role of proinflammatory cytokines in cisplatin-induced acute renal failure has been well documented, and elevation of the proinflammatory cytokines TNF-α and IL-1β as well as that of IL-6 has been demonstrated in humans with acute renal failure." (PMID 24171038, 2013). "CXCL2, CCL5, and TNFα were also reduced in HuSAP+ mice (relative to WT) 48 hours after Stx2 treatment and therefore may be crucial for the inflammatory pathology leading to acute renal failure." (PMID 21731756, 2011). "TNF and TLR4 are involved in regulating immune responses during kidney injury, whereas IGFBP7 serves as a marker for acute kidney injury." (PMID 41567268, 2026). "Further analysis demonstrated thatthe combination of TNF-α, interleukin 2, interleukin 6, and NGAL hadthe highest predictive value for acute kidney injury (area under the curve =0.93)." (PMID 40961276, 2025). "In murine sepsis-induced acute kidney injury (AKI), melittin significantly reduced renal cytokine expression (e.g., TNF-α, IL-6), suppressed NF-κB activation, and decreased lipid peroxidation markers such as 4-HNE and MDA, while upregulating Nrf2-HO-1 and other antioxidant pathways." (PMID 41301702, 2025). "In the LPS induced acute kidney injury (AKI) model, emodin substantially suppresses the activation of the NF-κB signaling pathway and diminishes the production of inflammatory cytokines, including TNF-α and IL-6." (PMID 41424782, 2025). "The TNF-α/HMGB1 inflammation signaling pathway plays an important role in pyroptosis during liver failure and acute kidney injury (AKI)." (PMID 37426664, 2023). "In acute kidney injury, IL-6 (interleukin-6), TNF-α (tumor necrosis factor-α), and IL-1 (interleukin-1) have a cardio-depressant direct impact." (PMID 37374112, 2023). "In a model of cisplatin-induced acute kidney injury, APF significantly reduced the levels of IL-1β, IL-6, TNF-α and MCP-1 by inhibiting the mincle/Syk/NF-κB signaling pathway." (PMID 37362082, 2023). "Moreover, vagal nerve stimulation mitigated acute kidney injury (AKI) and reduced TNF-α systemic levels in a mouse model, through α7 nicotinic acetylcholine receptors (α7nAChRs) positive splenocytes." (PMID 36798942, 2023). "ELISA assays in serum (NGAL; TNF-alpha, pi-GST) and urine (KIM-1, normalized to creatinine levels) also show low to moderate levels of acute kidney injury during the first 3 days after surgery." (PMID 36430283, 2022). "The levels of IL-6 and TNF-α correlated with the levels of creatinine and urea nitrogen, and were also higher in ARDS patients with acute kidney injury (AKI)." (PMID 34088317, 2021). "In the acute kidney injury study, inflammatory cytokines such as IL-1β, IL6, and TNF-α were measured in mice 16 h after intraperitoneal injection of LPS." (PMID 34327209, 2021). "It was concluded that biomarkers such as IL-6, IL-8, TNF-α, MMP-9 and NGAL are reliable acute kidney injury indicators." (PMID 34571700, 2021). "Chronic intestinal decontamination with rifaximin, non-absorbed gut-directed antibiotic, decreases the severity of acute kidney injury and HRS by reducing serum TNFα levels in patients with advanced cirrhosis." (PMID 33513830, 2021). "The present study was conducted from the perspective of M1 macrophage activation to explore the effect of the TNF‐α/HMGB1 pathway on pyroptosis in liver failure and acute kidney injury." (PMID 32419317, 2020). "High renal concentration of these inflammatory cytokines further promoted TNF-α-driven inflammation and CDDP-induced renal failure." (PMID 30866950, 2019).
acute kidney injury (continued). "G. vaginalis-exposed mice displayed higher levels of IL-1α, IL-1β, TNF-α, MIP-1β, and IL-2 in the kidney and higher levels of serum creatinine, a biomarker of acute kidney injury, than PBS controls." (PMID 28358889, 2017). "AKI: Acute kidney injury; CRS: Cardio-renal syndrome; EV: Extracellular vesicle; RAAS: Renin-angiotensin-aldosterone system; TNF: Tumour necrosis factor." (PMID 24451176, 2014). "The results of this study show there is an increase of serum TNF-α concentration during canine babesiosis, and the increased TNF-α concentration has an influence on the development of hypotension and renal failure in canine babesiosis." (PMID 24553975, 2014). "Synthesis of proinflammatory cytokines such as interleukin (IL)-1, IL-6 and tumor necrosis factor (TNF)-α, increasing in cell adhesion-molecule expression, development of oxidative stress are just some of the changes that occur during acute kidney injury." (PMID 24681567, 2014). "The results of this study show there is an increase in the serum TNF-α concentration in canine babesiosis and that the increased TNF-α concentration influences the development of hypotension and renal failure in canine babesiosis." (PMID 24553975, 2014). "Similarly, ALA alleviated acute kidney injury (AKI) in CLP rats by inhibiting NF-κB; downregulating proinflammatory cytokines (TNF-α, IL-6, IL-1β), iNOS, and HMGB1 expression in renal tissues; and reducing serum blood urea nitrogen (BUN) and creatinine levels." (PMID 40699721, 2025). "There were significant differences in the genotype frequency of TNF-α(-376 G/A) SNPS between S-acute kidney injury and non-acute kidney injury patients." (PMID 38716051, 2024). "Moreover, the marked anti-inflammatory actions of linagliptin have been characterized in an endotoxin-induced acute kidney injury model, where DPP-4 inhibition inhibited NF-κB pathway and the downstream pro-inflammatory cytokines IL-1β and TNF-α." (PMID 35890148, 2022). "In cisplatin-induced nephrotoxicity, increased expression of IL-1β was detected, which triggered the activation of IL-1R, inducing TNF-α production and leading to AKI, suggesting that knocking out IL-1 receptor holds the potential of decreasing cisplatin-induced acute kidney injury." (PMID 36552226, 2022). "The induction of IL-6 has been observed during the development of acute kidney injury (AKI) in humans and experimental animals alike, and IL-6 is produced in different amounts by endothelial cells in response to proinflammatory signals such as TNF-α." (PMID 36364876, 2022). "Although, some studies showed that treatments with TNF-α inhibitors have shown protective effects in the models of acute kidney injury (AKI) such as ischemia/reperfusion (I/R) injury, but there are few evidences about the effects of TNF-α blockers in the models of chronic kidney damage." (PMID 35647193, 2022). "In the study of acute kidney injury (AKI), as an upstream signal of inflammatory pathways, NF-κB and MAPK were activated by a series of inflammatory responses associated with AKI, leading to the production of large amounts of downstream inflammatory cytokines such as IL-6, TNF-α and IL-1β." (PMID 35744798, 2022). "In addition, the inhibition of the TNF-α/HMGB1 inflammatory signaling pathway suppresses macrophage pyroptosis to improve liver and kidney function during acute kidney injury and acute liver failure." (PMID 34749650, 2021). "TNFα and TNFRSF19: The pathogenic role of TNFα is observed in models of immune-complex-mediated glomerulonephritis, lupus nephritis, Antineutrophil Cytoplasmic Antibody (ANCA)-associated glomerulonephritis, DN, Acute Kidney Injury (AKI), and kidney allograft rejection." (PMID 34576149, 2021).
acute kidney injury (continued). "Others have also found that BMP7 treatment led to significant reductions in proinflammatory cytokines, including TNF, in macrophages in vivo and that BMP7 represses TNF and IL1B in models of chronic and acute renal failure and in chondrocytes from patients with osteoarthritis." (PMID 32973129, 2020). "Reperfusion after ischemia may cause injury through generation of reactive oxygen and nitrogen species, inflammatory responses by increased levels of tumor necrosis factor-α (TNF-α) and interleukins (IL), and apoptotic processes, and leads to acute kidney injury (AKI)." (PMID 31217925, 2019). "IL-12, IL-6, and TNF-α play a nonredundant role in determining the severity of acute kidney injury following IRI." (PMID 30013485, 2018). "In a cisplatin-induced acute kidney injury model, treatment with PLA2 attenuated tissue damage by reducing serum creatinine, blood urea nitrogen, production of pro-inflammatory cytokines, such as IL-6 and TNF-α, and macrophage infiltration." (PMID 26820468, 2016). "This study evaluated the effect of foot immersion with or without neck cooling on systemic proteins associated with acute kidney injury (NGAL, KIM-1), intestinal enterocyte damage (IFABP), immune activation (sCD14) and systemic inflammation (IL-6, TNF-α, CRP) in older adults." (PMID 41178782, 2025). "Release of many cytokines, including IL-1, IL-6, IL-8, IL 10, complement C3/C4, and tumor necrosis factor-α PCT, Leucocytes are characteristic of the inflammation and contribute to postoperative acute kidney injury (AKI)." (PMID 38888547, 2024). "Furthermore, among the analyzed markers, the NLR and MLR had shown a better predictive ability for survival in patients with cancer and acute kidney injury (AKI) in patients with severe acute pancreatitis compared to the classic inflammatory factors such as high-sensitivity CRP and TNF-α." (PMID 38156280, 2023). "ACE- angiotensin-converting enzyme, AKI- acute kidney injury, IL- interleukin, TLR- toll-like receptors, TNF- tumor necrosis factor, GM-CSF- granulocyte/monocyte-colony stimulating factor, G-CSF- granulocyte-colony stimulating factor." (PMID 32963910, 2020). "Hence, in addition to the TNF‐α inhibitors or neutralizing antibodies that are currently used for treatment, a combination of HMGB1 inhibitors or TNF‐α SNPs can also be considered for the treatment of liver failure and acute kidney injury." (PMID 32419317, 2020). "Both diabetic patients with or without kidney failure and non-diabetic patients with renal failure had increased TLR2 and TLR4 mRNA expression in association with increased levels of proinflammatory cytokines (TNF-α, IFN-γ, and IL-6) compared to normal subjects." (PMID 33442388, 2020). "A study of the acute renal failure mouse model showed that MSC administration could increase the recovery of renal function through the inhibition of production of proinflammatory cytokines, such as IL-1β, TNF-α, and IFN-γ." (PMID 31611920, 2019). "Thus, it seems probable that the observed strong correlation in this study between serum levels of TNF-α and renal indices such as FE(Na+) and UCr/SCr ratio result from the influences of decreased blood pressure and/or TNF-α on renal failure in canine babesiosis." (PMID 24553975, 2014). "Systemic infusion with MSCs also mediated a down-regulation of proinflammatory (TNF-α and IFN-γ) in several animal model including endotoxin-induced acute lung injury mice model, experimental autoimmune encephalomyelitis (EAE) and ischemia-reperfusion-induced severe acute renal failure model." (PMID 24558374, 2014). "In LPS treated renal tubular epithelial NRK-52E cells (AKI), emodin also inhibited LPS-induced TLR2, NF-κB, TNFα, IL-1β and IL-6 expression in vitro, which may contribute to the immune regulation of emodin in LPS-induced acute kidney injury." (PMID 35744949, 2022).